ERG (ETS transcription factor ERG)
Diseases named in the same sentence as ERG in open-access papers (continued):
Sharing a sentence is not in itself a finding about the gene and the disease.
tumor (continued). "In addition, we also analyzed the survival of genes which constituted PLP2+ Tumor EPCs score, and the results showed that only four of them (SPIB, ATF6, PLAGL1, ERG) were statistically significant (P<0.05)." (PMID 38482016, 2024). "Immunohistochemically, the tumor cells showed positivity for vimentin, CD31, and ERG." (PMID 38667451, 2024). "Immunohistochemical examination indicated that the tumor cells were CD34, CD31, and ERG." (PMID 39465747, 2024). "However, ERG showed an opposite function of enhancing AR-related pathways when PTEN, a phosphatase inhibiting the development of tumor by antagonizing the activity of phosphorylases, was lost." (PMID 38800374, 2024). "ERG, in concert with co-repressive proteins such as HDAC and EZH2, governs AR transcriptional activity, suppressing epithelial differentiation and fostering tumor progression." (PMID 38482016, 2024). "All ERG negative tumour areas (n=44) were mostly PSMA positive, with all being at least 90% IHC-PSMA positive, or a maximum of 10% PSMA%neg." (PMID 39083067, 2024). "The tumor was characterized by a MYC amplification, CD31 and ERG immunohistochemical positivity and was further characterized by using next generation sequencing (TruSight Oncology 500) in combination with the R-package XenofilteR to separate mouse from human sequence reads." (PMID 36788310, 2023). "Tumor cells exhibiting elevated ERG expression were categorized as ERG+, while cells lacking ERG expression were designated as ERG-." (PMID 37746302, 2023). "Analysis of the NPY system associations with ERG expression revealed higher Y5R EI in ERG-positive PCa than in ERG-negative tumours (p = 0.024)." (PMID 36583743, 2023). "In addition to being contiguous in space, this tumor showed homogeneous ERG expression, indicative of a TMPRSS2-ERG gene rearrangement." (PMID 37971875, 2023). "Some authors described that ERG-positive PCa cases have higher NPY expression than ERG-negative tumours." (PMID 36583743, 2023). "We also investigated whether these 5′-tRFs tumor subtypes of PRAD were driven by some key molecular events, such as androgen-regulated fusions of ERG or other ETS family members, or by other recurrent driver mutations." (PMID 36661724, 2023). "A total of 103 samples from 20 PCa patients were analyzed; foci of adjacent non‐tumor prostate tissue, HGPIN, GL3, GL4, GL5, and LN were examined to determine the presence of the TMPRSS2‐ERG fusion and ERG, EZH2, NKX3.1, and SPINK‐1 expression levels, using RT‐PCR." (PMID 36199157, 2023). "These analyses showed that the link between reduced PSAP expression and unfavorable tumor features was mainly driven by ERG-negative tumors." (PMID 37892063, 2023). "ERG+ and ERG− tumor cells and non-malignant LE cells all showed high expression of luminal markers KLK3, KLK2, and ACPP35." (PMID 35013146, 2022). "We observed a clear separation between ERG+ tumor cells and non-malignant LE cells while ERG− tumor cells were not clearly distinguishable from non-malignant LE in the analysis." (PMID 35013146, 2022). "Immunohistochemically, tumor cells were positive for AE1/AE3, CD31, FLI-1 and ERG." (PMID 34514569, 2022). "High expression of JUP was associated with adverse tumor stage, high Gleason grade lymph node metastases in a subset of PCa patients without TMPRSS2:ERG fusion." (PMID 36387263, 2022). "The analysis of a cohort of 195 men showed that the expression of PCA3 and ERG genes (including the fusion gene TMPRSS2:ERG) normalised to the level of SPDEF (SAM-pointed domain-containing Ets transcription factor) can be used to differentiate between GS ≤ 6 and GS ≥ 7 tumours." (PMID 34811504, 2022). "Non-uniform CNV profiles were detected within ERG+ and ERG− tumor cell populations, suggesting heterogeneity in both tumor cell populations." (PMID 35013146, 2022). "Therefore, the roles of ERG-cg27071152-MTURN and FOXM1-cg19212949-PTPR in different tumor stages and in LUAD progression were explored." (PMID 36550923, 2022).
tumor (continued). "While ERG+ tumor cells clustered separately from non-malignant LE cells, ERG− tumor cells resided more closely to non-malignant LE cells in the UMAP of all epithelial cells." (PMID 35013146, 2022). "The tumor was positive for CD117, Vim, CD56 and NSE and showed focal expression of desmin but was negative for myogenin, S-100, SYN, INSM1, CD34, STAT6, INI-1, Brachyury, ERG, TLE1, AE1/AE3, WT-1, CD99 and SMA." (PMID 35488288, 2022). "ERG-negative tumor cells, compared to ERG-positive cells, demonstrate shared heterogeneity with surrounding luminal epithelial cells and appear to give rise to common tumor microenvironment responses." (PMID 35013146, 2022). "Immunohistochemically, the tumor cells were positive for CD117, vimentin, CD56 and NSE and focally expressed desmin; the cells were negative for myogenin, S-100, SYN, INSM1, CD34, STAT6, INI-1, Brachyury, ERG, TLE1, AE1/AE3, WT-1, CD99 and SMA." (PMID 35488288, 2022). "Immunohistochemically, the tumor cells were diffusely and strongly positive for ERG while negative for S100, α-SMA, CD34, and other vascular markers." (PMID 36591513, 2022). "The concordance levels were 100% between intraductal lesions and the adjacent invasive tumours, but not for HGPIN (of the ERG-positive invasive tumours, only 6% [1/11] were associated with ERG-positive HGPIN)." (PMID 35159086, 2022). "ERG + tumor cells clustered in a patient-specific manner, whereas no such pattern was seen for ERG− tumor cells as most ERG− tumor cell states comprised more than one patient." (PMID 35013146, 2022). "As expected, ERG and SPINK1 overexpression were mutually exclusive at each tumor focus." (PMID 35050902, 2022). "Tumor cells exhibited strong, diffuse cytokeratin expression as well as CD31 and ERG." (PMID 36726928, 2022). "Tumour cells characteristically express fusion proteins with an N-terminal region derived from EWS, a poorly characterised RNA-binding protein, and C-terminal region from FLI-1, or less frequently ERG, including the ETS domain." (PMID 34066106, 2021). "Notably, RWPE-1 cells receiving ERG/PTEN-derived EVs had significantly higher level of miR-322 and enhanced ability to form tumor-sphere compared to cells treated with WT prostate-derived EVs." (PMID 33500545, 2021). "In addition, TAK-242 treatment in vivo was able to reduce BrdU incorporation in ERG-AKT tumors, indicating that proliferation rate is a primary mechanism of the reduced tumor size elicited by TAK-242." (PMID 33554122, 2021). "We found that a phosphomimetic mutant, S96E ERG, drove tumor formation and clonogenic survival without activated AKT." (PMID 34314419, 2021). "In addition, the SPOP protein plays a role as a tumor suppressor that negatively regulates the stability of multiple other oncogenic substrates in PrCa, including AR, SRC-3, c-MYC, ERG, DEK, BRD4 and Trim24." (PMID 34857003, 2021). "Because of the relatively high percentage of patients with low JUP expression in the absence of ERG rearrangement (see 3.3), the correlation analysis of JUP and tumor features was repeated in ERG‐negative and ERG‐positive patient subsets." (PMID 33533127, 2021). "Among others, PD-L1, ERG, Integrin-β5, Survivin, TGF-β, phosphorylated-TSC2 as well as partners of the MAP-kinase and mTOR pathways emerged as differentially expressed endpoints in tumor-derived EVs." (PMID 34155195, 2021). "Notably, IDC tumor in PDXs maintained its morphological features, such as a cribriform, as well as molecular features, including AMACR- and ERG-positive luminal cells and p63-positive basal cells." (PMID 34884926, 2021). "Tumor cells demonstrated positive IHC expression for CD34, CD31 and ERG IHC stains." (PMID 33593408, 2021). "They identified tumor cells positive or negative for ERG expression by immunohistochemistry (IHC) staining, followed by isolation of negative and positive cell populations with microdissection (LCM)." (PMID 34638309, 2021).
tumor (continued). "Previous studies reported that FOXM1, ERG, and MYBL2 played a role in tumor immune infiltration." (PMID 34489925, 2021). "A prognostic role of YAP1 expression was observed in subsets of both ERG positive and ERG negative cancers, althougth stronger in ERG negative tumours." (PMID 32488048, 2020). "By immunohistochemistry, the tumor cells stained positively for S-100 (focal +), CD34 (strong +++) and Ki-67 (20%), and negatively for smooth muscle actin, pan-cytokeratin, neurofilament, pan-cytokeratin-L, GFAP, CD31, STAT6, ERG, myogenin, and MyoD1." (PMID 32590748, 2020). "Our analysis of molecularly defined tumor subgroups revealed that the prognostic impact of TFAP2D expression was almost entirely driven by ERG negative cases." (PMID 32143573, 2020). "On immunohistochemistry (IHC), all 7 cases expressed vascular markers CD31, CD34 and ERG confirming the endothelial lineage of tumor cells and were negative for epithelial markers of CK AE1/AE3, Cam 5.2, CK7 and CK 20, Glypican3 and Hep par1." (PMID 32977811, 2020). "The tumour was positive for CD99, ERG, CD56, Synaptophysin, PanCK, Cam5.2." (PMID 32450834, 2020). "Our analysis of molecularly defined tumor subgroups revealed that the prognostic impact of SFRP4 expression was almost entirely driven by the ERG negative cancer subgroup." (PMID 32677026, 2020). "It showed that associations between SFRP4 and tumor phenotype (p ≤ 0.05 each) and PSA recurrence (p < 0.0001) were largely driven by the subgroup of cancers lacking ERG fusion." (PMID 32677026, 2020). "Given this considerable difference associations between the CD138 expression, tumor phenotype and PSA recurrence were separately analyzed in ERG positive and negative cancers." (PMID 33195694, 2020). "All 23 matched biopsy and RP samples were concordant for ERG expression (18 were ERG-negative and 5 were ERG-positive), providing confidence that similar tumor foci were being compared before and after treatment." (PMID 32203069, 2020). "Persistent suppression of ERG expression is clearly not a signal for continued anti-tumour effectiveness of the AI: assessment of these genes as a pharmacodynamics marker in this instance would likely be misleading." (PMID 30563991, 2019). "The tumor cells were diffusely positive for CD34, STAT-6 and FLI-1, and negative for pan-cytokeratin, CAM5.2, p63, S100 protein, CD31, SMA, and calponin.ERG and Ki67 immunostaining showed an accentuated nuclear staining pattern in the central dedifferentiated area." (PMID 30777087, 2019). "The tumor cells were strongly and diffusely positive for AE1/AE3, FLi-1, ERG and FOSB." (PMID 31311568, 2019). "The frequency of CDH1 deletions increases with tumor grade and is markedly higher among ERG fusion-negative cancers than among fusion-positive cancers." (PMID 31366128, 2019). "Overall, the data suggest that tumor relevant functions of ELAC2 and other proteins might be modulated by the ERG fusion status." (PMID 31452838, 2019). "Methylation of ETNK2, NTN1, and NUDT10 was increased in ERG-fusion negative tumors, which is concordant with the significant loss of TET2 expression in these tumor samples." (PMID 30917865, 2019). "This revealed a tighter relationship of high PTPN12 staining levels with unfavorable tumor features in ERG negative than in ERG positive cancers." (PMID 31606028, 2019). "Loss of ZIC2 expression was also linked to Gleason grade, advanced pathological tumour (pT) stage, lymph node metastasis and higher preoperative PSA levels in all cancers (p < 0.0001, each) and in the subset of ERG-fusion negative tumours (data not shown)." (PMID 31640781, 2019). "Immunohistochemistry supported the morphological assessment, with the tumour cells expressing ERG, CD31 and VE-cadherin, but not PDGFR-β." (PMID 31221668, 2019). "Further, it has been recommended that this particularly applies if on immunostaining the tumours are ERG positive and PTEN negative, which is the typical immunoprofile of IDCP." (PMID 30825003, 2019).
tumor (continued). "Our analysis of molecularly defined tumor subgroups revealed that the prognostic impact of BAP1 was almost entirely driven by the ERG negative subset." (PMID 31903168, 2019). "In summary, both ERG and PTEN knockdown resulted in increased growth and invasion but the combination of ERG expression and PTEN knockdown leads to the fully transformed phenotype manifested by colony formation in soft agar and tumor formation in immunocompromised mice." (PMID 29581856, 2018). "The genomic alteration patterns detected in ERG-negative group showed similarities with 77.5% of tumor samples of African American patients." (PMID 30150711, 2018). "Among these, we investigated whether soluble factors and hypoxia reduce the expression of ERG and FLI1, as aberrant soluble factor profiles and hypoxia are key characteristics of the tumor microenvironment." (PMID 30500808, 2018). "In order to elucidate the expression correlation between ERRα and ERG in the progression of castration-resistant prostate cancer (CRPC), we established a CRPC xenograft tumor model VCaP-CRPC based on the castration-relapse growth of AR- and T:E-positive VCaP cells." (PMID 30042415, 2018). "The absence of statistical relationship to TMPRSS2:ERG fusion status, chromosomal deletion or high tumor cell proliferation argues against a major role of PSCA for regulation of cell cycle or genomic integrity." (PMID 29855276, 2018). "Moreover, we demonstrated that ERG and FLI1 expression is downregulated in ECs within tumors by soluble factors enriched in the tumor microenvironment." (PMID 30500808, 2018). "Our study highlight that BCAR1 expression is associated with unfavorable tumor features and that the prognostic impact of BCAR1 is limited to ERG-negative cancers." (PMID 29304771, 2018). "Finally, we show that ERG and FLI1 expression is decreased in ECs within tumors, suggesting that EndMT is induced in the tumor microenvironment." (PMID 30500808, 2018). "We compared the expression profiles of ERG-positive, ERG-negative tumor and prostate tissue samples with morphologically normal appearance to identify differentially expressed genes among these three groups." (PMID 30150711, 2018). "Furthermore, we also show that ERG and FLI1 expression is downregulated in tumor tissues by soluble factors." (PMID 30500808, 2018). "In addition, in contrast to the normal prostate, VIM-positive fibroblast-like cells were abundant in both PB-MYC and ERG/PTEN prostates, filling up the space between tumor ducts." (PMID 27935821, 2017). "Furthermore, double rearrangements of ERG with TMPRSS2 and SLC45A3 or NDRG1, well known androgen-induced genes, have been found to coexist in the same tumor in a subset of PrCa cases." (PMID 29088771, 2017). "ERG positive immunostaining was found in 103 tumor samples (46.8%), and it was absent in 117 (53.2%)." (PMID 29088771, 2017). "In ten tumor patients, ERG-positive small areas of non-neoplastic appearing prostatic epithelium were also seen." (PMID 27530104, 2016). "That this percentage remains at comparable levels (14–36 %) irrespective of the tumor focus size is not surprising as cancers that were initially ERG positive are unlikely to loose TMPRSS2-ERG fusions during tumor progression." (PMID 27530104, 2016). "A detectable difference in cancer morphology (i.e., gland size, gland architecture, gland density and tumor cell morphology) was not seen between ERG positive and negative cancer foci." (PMID 27530104, 2016). "In contrast to tumor samples, multiple rearrangement patterns were present in ERG-rearranged CTCs regardless of the CTC isolation technique, with gain of native ERG far more prevalent." (PMID 27391263, 2016). "Remarkably, six of the 42 homogeneously ERG-positive tumor foci (14.3%) harbored small 6q15-deleted areas, but none of the 34 6q15-deleted foci showed areas of ERG positivity (p = 0.022)." (PMID 26684029, 2016).
tumor (continued). "The decreasing prevalence of completely ERG negative foci from 70 % to about 50 % with increasing tumor focus size suggest that subclones with TMPRSS2-ERG fusion develop in about 30 % of initially ERG negative cancer foci." (PMID 27530104, 2016). "Here, we have determined a comprehensive miRNA expression profile in ERG-positive, and ERG-negative CaP tumor tissue." (PMID 26988912, 2016). "ERG expression was detected in the nucleus of tumor cells but not in paired normal prostatic tissues, whereas PTEN expression was observed in the cytoplasm and nucleus of tumor cells and in normal prostatic glands." (PMID 25897494, 2015). "We found no rearrangements associated with ERG, ETS, or their reported fusion partners in the CTCs or tumor tissues." (PMID 26575023, 2015). "In addition, in 1 GBM where ERG only stained endothelial cells, CD34 stained both endothelial and tumor cells." (PMID 25881913, 2015). "As the tumor sets were very large, statistical differences between the ERG positive and negative groups were still highly significant (p < 0.0001)." (PMID 25762627, 2015). "In contrast, no unequivocal differences were found between SOX9 levels and tumor phenotype in ERG-negative cancers, although significant p-values were still obtained due to the very high number of samples in our study." (PMID 26030748, 2015). "It has been previously demonstrated that the TP63/TP53L, ERG, GRHL1/Get-, HNF1A/TCF-1, SPI1/PU.1, WT1 and GLIS2, FOXM1 and FOXP3 transcription factor networks, which are mediated by HNF4A, can regulate the expression of Trop2 in tumor tissues." (PMID 25779928, 2015). "Borno and co-workers however, also identified a miRNA-dependent mechanism for EZH2 overexpression in TMPRSS2:ERG negative tumours." (PMID 25496077, 2014). "Moderate/high CRISP3 protein expression was present in 217/316 (69%) in ERG positive vs. 287/496 (58%) in ERG negative tumor cores (p = 0.002)." (PMID 24606912, 2014). "In another cohort of 2800 PCas, no relation was found between the ERG gene rearrangement and the clinical outcome or tumor phenotype." (PMID 23708091, 2013). "None of these genes showed significant expression differences between PCa ERG+ and PCa ETS−, suggesting that ERG proteins do not regulate their expression in this tumor type." (PMID 23185447, 2012). "P08-029pre, which came from a small tumor volume of 0.6 cc, showed marginal increase (2- to 3-fold above background) for these genes except for AMACR: AGR2 = 0.16, AMACR = 0.32, CRISP3 = 0.78, ERG = 0.28, HPN = 0.12, PCA3 = 0.19." (PMID 23029164, 2012). "We further show that CRISP3 is a direct target of overexpressed ERG, suggesting that CRISP3 may be a mediator of tumor progression driven by the TMPRSS2-ERG rearrangement." (PMID 21814574, 2011). "Quantitative Real-Time PCR analysis of an ERG-positive tumour and the corresponding non-tumoral adjacent tissue validated the connection between ERG and PIM1 at the transcriptional level." (PMID 22140532, 2011). "Specificity was demonstrated by the absence of binding of ERG to the ETS2 promoter in the tumor samples." (PMID 20479932, 2010). "With increasing expression of Hsp-27 there was a progressive decline in ETS-gene rearrangement frequency (χ2(trend)=31.4, P<0.001), such that most of the strongly staining cancers were found in ERG non-rearranged tumours." (PMID 19707199, 2009). "Targeted immunohistochemistry showed tumor cell positivity for cytokeratin, nuclear beta-catenin, CD56, dot-like CD99, progesterone receptor (focal), and aberrant focal CD31 expression, with negativity for ERG and other vascular markers, confirming the diagnosis of SPN." (PMID 41859616, 2026). "Interestingly, most tumor cells in AS co-expressed PDPN and markers of blood vessel phenotypes (e.g., CD31, ERG, vWF), an unusual combination in normal vessels, suggesting their potential derivation from a common precursor of lymphatic and blood vascular endothelium." (PMID 40666093, 2025).